BRAF (B-Raf proto-oncogene, serine/threonine kinase)
Diseases named in the same sentence as BRAF in open-access papers (continued):
Sharing a sentence is not in itself a finding about the gene and the disease.
tumor (continued). "Herein, we reported that AIM2 expression was lower in BRAF-mutant than that in BRAF wild-type CRC tumor tissues." (PMID 33842454, 2021). "Among the 9789 CRC cases with tumor data available, 11% of the tumors were BRAF-mut, 34% KRAS-mut, 15% MSI-H, and 18% CIMP+." (PMID 34377935, 2021). "The emergence of a population resistant to the BRAF inhibitor was associated with an increase in CSF-1R and IL-34 expression, and activation of ERK1/2 and AKT signaling pathways to promote tumor survival and proliferation." (PMID 33408768, 2021). "Combined BRAF/MEK inhibition led to a dramatically lower tumor burden in both BP and BPN mice when assessed after 2 weeks and 4 weeks of MAPKi treatment." (PMID 33821796, 2021). "One of these studies, conducted in xenograft models with BRAF-mutant tumours, showed that treatment with vemurafenib (a specific BRAF inhibitor) was enough to reverse resistance to EGFR inhibitors." (PMID 34359657, 2021). "Targeted therapy (BRAF/MEK inhibitor) has a rapid anti-tumor effect and is of benefit to the majority of patients." (PMID 34359813, 2021). "In the nude mice tumor-bearing model, inhibition of BRAF activity decreases tumor growth, which indicated that BRAF played a key role in tumor proliferation." (PMID 33622273, 2021). "The BRAF gene encodes a protein kinase (MAPK) that regulates cellular growth and proliferation in tumor cells." (PMID 34537078, 2021). "While BRAF activation contributes to tumor development and progression in the neural stem cells and progenitor cells of Homo sapiens, BRAF mutations are detected in adult diffuse gliomas and are associated with poor outcomes." (PMID 33980169, 2021). "The analysis revealed 91% concordance both between the qPCR and NGS results in tumor samples (inter-platform concordance) and between tumor and plasma NGS analysis of the BRAF mutation status of the same patient (inter-tissue concordance)." (PMID 34356096, 2021). "Several different 5′ fusion partners for oncogenic BRAF exist in different cancers and vary by tumor type." (PMID 34575554, 2021). "In conclusion, we established novel canine TCC cell lines from two tumor tissues and one metastatic lymph node of canine TCC patients harboring BRAF V595E mutations." (PMID 34502061, 2021). "Because different frequencies of BRAF mutations in CRC have been reported depending on tumour location, we extracted the molecular data of conventional colorectal ACs matched by tumour location with the colorectal NEC group." (PMID 33737597, 2021). "Despite BRAF inhibition, the MAPK pathway can be activated due to mutations in the NRAS gene, promoting tumor survival." (PMID 34575876, 2021). "Our data demonstrated that SIRT3 knockdown abrogated tumor growth and/or tumor establishment abilities in BRAF-mutant G361-xenografted mouse model." (PMID 33937086, 2021). "In colorectal cancer studies, BRAF, PIK3CA, and KRAS mutations in different CTCs were found, suggesting the existence of a large level of tumor heterogeneity both between individuals and within the same individual." (PMID 34412644, 2021). "In conclusion, we found that SMAD4 mutation was associated with poor prognosis in CRC, but has nothing to do with MSI status, BRAF status or tumor grade." (PMID 34301194, 2021). "When assessing the treatment response in the RAS and BRAF wildtype cohort there was a clear difference in response to anti-EGFR for the CMS4 tumours between both trials." (PMID 34253874, 2021). "In both NKX2-1-positive and NKX2-1-negative tumors, combined BRAF/MEK inhibition leads to substantial tumor regression, but drug-tolerant cells persist with the potential to relapse." (PMID 33821796, 2021). "By itself, pmel-1 ACT had modest activity, but once combined with BRAF-MEKi, substantial tumor control was observed." (PMID 34944961, 2021).
tumor (continued). "In conclusion, dabrafenib and trametinib caused marked tumor shrinkage, improvements in QOL, and prolonged survival when administered to an “oldest old” patient with BRAF V600E‐mutant NSCLC." (PMID 33215864, 2021). "The tumour responded rapidly and significantly to BRAF/MEK inhibitors, and the patient's symptoms improved within 2 weeks." (PMID 34484797, 2021). "Treatment of the PDX by the MEK inhibitor trametinib, resulted in a marked anti-tumor activity, in contrast to the BRAF inhibitor and the different chemotherapies that were ineffective." (PMID 34496925, 2021). "As for primary tumor gene mutations, 14 patients had a RAS mutation, 1 patient had a BRAF mutation, and 18 patients had RAS/BRAF wild type." (PMID 34692541, 2021). "Although somatic mutational changes within the BRAF, NRAS, NF-1, and KIT genes are seen to deregulate tumor biology within the melanocytes, acknowledgment of the contributory role of inherited factors is also due." (PMID 34155457, 2021). "We previously demonstrated that MEK/ERK activity is sufficient to induce p21CIP1 and that the MEK/ERK activity in BRAF-mutant tumor cells can be routed to induce p21CIP1 expression." (PMID 34947982, 2021). "Tumor mutations identified included BRAFV600E in 27 (54%), MAP2K1 in 6 (12%), KRAS in 3 (6%), non-V600 BRAF in 3 (6%), and others." (PMID 33057928, 2021). "On the one hand, a combination of targeted therapy (TT) with BRAF and MEK inhibitors can be proposed for patients with a BRAF V600 mutation-bearing tumor." (PMID 34359281, 2021). "At present, there are approved drugs for lung cancer, targeting tumor cells with mutated EGFR, ALK and ROS1 fusions, and mutated BRAF." (PMID 34217228, 2021). "In 50% of patients with mutant BRAF, BRAF/MEK inhibitors can modify the tumour immune microenvironment to enhance ICI efficacy." (PMID 34359633, 2021). "In vitro experiments on cell lines have shown that R8/siBraf can enhance siBraf transfection, silence the BRAF gene and inhibit tumor cell growth." (PMID 33546290, 2021). "Next to the antiproliferative effects of BRAF/MEKi, accumulating preclinical evidence suggests that BRAF/MEKi exert immunomodulatory functions such as paradoxical ERK activation as well as additional effects in non-tumor cells." (PMID 34576054, 2021). "Mice inoculated with BRAF-mutant A375 cells were treated with G9, vemurafenib or their combination, and tumor growth was assessed over a 3-week treatment period." (PMID 33613844, 2021). "The number of cases in each study varied from 23 to 513, cancer prevalence from 16 to 56%, PTC rate from 1 to 56% and rate of BRAF positive PTC tumours from 0 to 24%." (PMID 32638211, 2021). "We did not observe significant correlations between the presence of RET mutations and primary tumor location and RAS or BRAF status, on the other hand." (PMID 34741450, 2021). "The clinical response to BRAF inhibition was typified by rapid and robust tumor regression in almost all patients treated, with very minimal toxicities." (PMID 34025662, 2021). "Experiments performed on BRAF-mutant tumor cell lines and their xenografts showed that sequential monotherapy is ineffective because it leads to the parallel evolution of resistant BRAF-amplified clones." (PMID 33924486, 2021). "Previously we have shown that DTP elicited a robust anti-tumor response against YOVAL1.1 in vivo with overall survival of beyond 100 days compared to approximately 70 days for BRAF-MEKi." (PMID 34944961, 2021). "This variable proportion is linked to pathological variants, classic PTC tumours being more often BRAF positive than other PTC variants, and to the geographical origin of patients with Koreans showing very high proportions of BRAF mutated PTC tumours." (PMID 32638211, 2021).
tumor (continued). "The correlation between each of these checkpoints and their tumour‐secreted ligands would be interesting to explore, as well as relating each immune checkpoint to the T‐cell subset it is most highly expressed in, and whether there are any underlying associations with common mutations such as BRAF." (PMID 33338327, 2021). "Several studies have highlighted the presence of BRAF in clinically and histopathologically aggressive tumours." (PMID 34734568, 2021). "ERK pathway suppression detected with NanoString gene expression was observed more commonly in those with BRAF-mutant tumours compared to those with KRAS-mutant tumours." (PMID 35582302, 2021). "The studies have revealed that BRAF inhibitors result in paradoxical increased MAPK signaling and tumor development through the activation of RAS mutations in BRAF wild‐type tumor cells." (PMID 32881028, 2021). "Among the patients with a KRAS/BRAF tumor tissue mutation, KRAS/BRAF mutations were detected in plasma cfDNA in 93% of patients with CRC‐LM compared to 20% of patients with CRC‐PM (p < 0.0001)." (PMID 33635598, 2021). "Particularly for CM, it was observed that rechallenging patients with BRAFi after a free period of treatment and tumor progression resulted in a significant clinical response upon BRAFi and BRAF + MEKi treatments." (PMID 34575678, 2021). "By contrast, it was almost equal to BRAF AF in the LR-Om (45% versus 49%) and equal in the KR lesion (both 39%), correlating with the tumor purity of both lesions." (PMID 34301805, 2021). "On the other hand, Ocoxin reduces fibroblast-mediated tumor progression by means of overcoming resistance against targeted therapy with the BRAF inhibitor and impairing fibroblast-mediated tumor cell migration." (PMID 33669949, 2021). "Meanwhile, BRAF mutations, together with alterations of TGFBR, IGF2R, and BAX, promote tumour progression toward intermediate and late states of carcinogenesis." (PMID 34359657, 2021). "They suggested that as PTC develops, the proportion of tumor infiltrating immune cells increases significantly, especially in BRAF V600E positive cells." (PMID 34680332, 2021). "Studies have found poorer OS in mutant KRAS and BRAF tumours in patients with locally advanced and metastatic disease." (PMID 34940086, 2021). "All the patients underwent PET/CT scan before primary tumor resection, pathological samples were obtained, and the KRAS/NRAS/BRAF mutational status was evaluated." (PMID 34239564, 2021). "Based on the tumour microbiome, we stratified CRC patients into three subtypes, significantly associated with prognostic factors such as tumour grade, sidedness and TNM staging, BRAF mutation and MSI status." (PMID 34638284, 2021). "The authors propose that driver mutations in BRAF and RAS dictate downstream signalling cascades which is reflected in both the histopathological features and molecular genetics of the tumour." (PMID 34441338, 2021). "Somatic mutations of BRAF and NRAS result in the hyperactivation of mitogen-activated protein kinase (MAPK) signaling that drives tumor growth and leads to progression of the disease." (PMID 34209415, 2021). "The percentage of patients with the number of tumor mitoses per mm2 greater than 5 was higher in the BRAF+ group (38% vs 21%, p = 0.036)." (PMID 34537078, 2021). "Regarding BRAF_V600E mutation status, no evident difference was found between the wild-type BRAF patients and mutant-type BRAF patients in tumor purity." (PMID 34925437, 2021). "In contrast, paradoxical activation in macrophages leads to the production of VEGF, which promotes tumor growth and resistance to BRAF inhibition." (PMID 34025662, 2021). "They tested the common clinicopathological parameters (ulceration, mitotic count, and tumor regression), BRAF immunoreactivity, and cell motility involving actin-modulating proteins, in relation to SLN involvement and survival." (PMID 34209415, 2021).
tumor (continued). "This BRAF mutation also counters any therapeutic effect from the EgA1 anti-EGFR component in the LiTE that also blocks EGFR signalling and tumour growth." (PMID 33686177, 2021). "An inferior survival after relapse for the panitumumab treated patients was observed, especially for the population with a mutation (either KRAS, BRAF, NRAS or PIK3CA), possibly due to accelerated tumour growth caused by the anti-EGFR therapy." (PMID 34253874, 2021). "The concentration of BRAF(V600E) ctDNA decreased along with tumor reduction and increased in a case of relapse." (PMID 34575876, 2021). "In fact, rechallenge treatment with anti-EGFR drugs has shown promising clinical activity, particularly in patients with plasma RAS and BRAF wild type circulating tumor DNA, as defined by liquid biopsy analysis at baseline treatment." (PMID 33920531, 2021). "Another interesting finding is that HER3, a member of the EGFR family, is able to reactivate RAS-ERK signaling, allowing tumor cells to escape from the inhibitory effects of BRAF inhibitors." (PMID 34809598, 2021). "TERT promoter mutations generally occur late in tumor genesis, after the appearance of driver mutations in other oncogenes such as RAS/BRAF, EGFR, which lead to constitutive cell division and thus accelerate telomere erosion." (PMID 34944589, 2021). "Given this tumor oncogene addiction, several selective BRAF inhibitors (BRAFi, dabrafenib/vemurafenib) were successfully developed." (PMID 33391536, 2021). "The results suggest that BRAF mutant tumor tissues carry more stromal cells, more immune cell infiltration, and had lower tumor purity." (PMID 34381786, 2021). "Due to the introduction of BRAF- and MEK-inhibition, this mutation has become a target for anti-tumor treatment." (PMID 34572865, 2021). "Paired tumor biopsies in patients with CRC harboring BRAF-V600E mutations and treated with triple-pronged therapy targeting BRAF, EGFR, and MEK showed that an increase in T-cell infiltration occurred after blockade of the MAPK pathway via BRAF inhibition." (PMID 34944931, 2021). "In the PTMC group, BRAF V600E tumours were found to have a significantly greater occurrence of tall cell variants (p = 0.031) and having greater than one aggressive feature (p = 0.012)." (PMID 34742355, 2021). "The translational potential of this combination is strengthened by the growing identification of oncogenic mutations in HRAS, KRAS (HGNC IDs 5173, 6407), NRAS and BRAF (HGNC ID 1097) genes in SS cell lines and clinical tumor subsets." (PMID 34857011, 2021). "The MEK–ERK–BRAF pathway has been highlighted by clinicians because the efficacy of BRAF and/or BRAF-related pathway inhibition dramatically improves anti-tumor effects." (PMID 34829495, 2021). "In our work, the tumor-promoting M2-like phenotype was robustly validated and confirmed through different methodologies, markers, and by the use of two BRAF-mutant cell lines derived from ATCs." (PMID 34638305, 2021). "The authors noted increased influx of immune cells into the tumor and tumor regression upon oncogenic inactivation, and identified BRAF and MYC as key mediators of KRAS-induced immune evasion." (PMID 34957115, 2021). "The acquired resistance to BRAF inhibitors is maintained by IGF1R-driven tumour vascular reconstruction." (PMID 34923978, 2021). "Studies implicate that CRAF is vital for mutant KRAS signal transduction and tumor initiation other than BRAF." (PMID 34301278, 2021). "BRAF amplification demonstrates another potential mechanism of K-Ras activation which provides tumor cells with the ability to overcome their sensitivity to MEK inhibition." (PMID 33807778, 2021).
tumor (continued). "Among patients with known BRAF V600E mutant tumors, absolute BRAF V600E copy number in tumor tissue ranged from 80–638 and BRAF WT copy number ranged from 129–1391." (PMID 33799709, 2021). "These different subtypes classify tumours with distinguishing features such as microsatellite instability (MSI), high/hypermutated/BRAF mutated (CMS1), WNT activated (CMS2), metabolic/KRAS mutated (CMS3) and EMT/TGF-β activated (CMS4)." (PMID 33879799, 2021). "Our study found that MET genomic alterations were statistically related to age and tumor stage and co-existed with mutations of other oncogenic driver genes, such as EGFR and BRAF." (PMID 34660325, 2021). "BRAF and NRAS mutations were found to be independent prognostic factors of poor OS in our cohort of CRC patients with tumor recurrence." (PMID 33919924, 2021). "Mutations involving effectors of the mitogen-activated protein kinase (MAPK) pathway such as RET, BRAF, RAS, and NTRK1 occur in approximately 70% of patients with PTC and are associated with histopathological and biological tumor behavior." (PMID 34325712, 2021). "The main targetable genetic aberrations (IDH1 and BRAF mutations, FGFR fusions, HER2 amplification) can be identified in circulating tumour DNA (ctDNA) in around 20% of BTC patients." (PMID 33660222, 2021). "Overall, our data demonstrated the restoration of AIM2 expression inhibits the tumor growth and metastasis of BRAF- mutant CRC in vivo." (PMID 33842454, 2021). "Bypass signaling activation by BRAF activation leads, in tumor cells, to increased cell survival and proliferation, while apoptosis is decreased." (PMID 34575554, 2021). "Regorafenib inhibits multiple tyrosine kinases involved in tumor angiogenesis (VEGFR1-3, TIE2), oncogenic transformation (KIT, RET, RAF1, BRAF), and shaping tumor microenvironment (PDGFR, FGFR)." (PMID 34527573, 2021). "Although the anti-tumor effects of BRAF inhibitors are impressive, the durability of the response is limited due to drug resistance." (PMID 34526609, 2021). "The gain-of function mutations of BRAF and NRAS lead to constitutive activation of the signaling of the mitogen-activated protein kinase (MAPK) pathway and thus to tumor proliferation and progression." (PMID 34698264, 2021). "The KRAS/NRAS/BRAF are the downstream effectors of the EGFR signal pathway involved in tumor cell proliferation, differentiation, and invasion." (PMID 34395262, 2021). "The higher the positive expression rate of BRAF, the lower the survival rate later tumor staging of patients." (PMID 33622273, 2021). "Given the abundance of DNA in tumor tissue, the BRAF V600E and BRAF WT ddPCR assay with the DNA primer set (i.e., ddPCR Tumor Assay) was used to test patient tumor samples." (PMID 33799709, 2021). "Sequencing of tumor DNA, such as Sanger sequencing and pyro-sequencing, is a common method for identifying BRAF variations." (PMID 34613404, 2021). "In 2015, a pilot trial of combined vemurafenib and panitumumab in BRAF-mutant mCRC patients post chemotherapy reported that the treatment limited tumour progression and resulted in modest clinical activity." (PMID 34663410, 2021). "Vemurafenib inhibits BRAF kinase activity by competing with ATP at the kinase domain, resulting in cell apoptosis and decreased tumor growth." (PMID 33807778, 2021). "Other important factors include CpG island methylator phenotype status, BRAF and KRAS mutational status, tumor differentiation (grade), location (right-sided vs. left-sided), and colon microbiota." (PMID 35008550, 2021). "We observed that the MSKCC MSI-CRC cohort also included patients (64/97, 66%) with either a BRAF, NRAS, or KRAS mutation, whereas our MSI-CRC cohort was entirely composed of BRAF/NRAS/KRAS wild-type tumours." (PMID 34282766, 2021).